FLI1 (Fli-1 proto-oncogene, ETS transcription factor)
Diseases named in the same sentence as FLI1 in open-access papers (continued):
Sharing a sentence is not in itself a finding about the gene and the disease.
breast carcinoma (continued). "The results of the present study revealed that FLI‐1 is a novel and an extremely useful predictor for the poor prognosis in patients with breast cancer." (PMID 29869379, 2018). "In the future, by reducing the number of tumor cells and extending the feeding time, we hope to obtain the expected result, that is, FLI‐1 can promote the metastasis of breast cancer in vivo." (PMID 29869379, 2018). "Down-regulation of miR-200 s predicts a poor outcome in breast cancer patients via elevated expression of Fli-1 and TGF-β, contributing to ECM remodeling and triggering breast cancer cell invasion and metastasis both in vitro and in vivo." (PMID 28851377, 2017). "For example, FLI1 repositions in 100% (10/10) of breast cancers and 92.9% (13/14) of prostate cancers, rates far too high to suggest it can be used to stratify indolent and aggressive cancers." (PMID 27507988, 2016). "This study for the first time identifies FLI1 as a clinically and functionally important target gene of metastasis, providing a rationale for developing FLI1 inhibitors in the treatment of breast cancer." (PMID 26156017, 2015). "The abundance of FLI1 protein was strongly correlated with the advanced stage, poor differentiation, and lymph node metastasis in breast cancer patients." (PMID 26156017, 2015). "Our findings thus support a distinct paradigm for the involvement of FLI1 in the progression of breast cancer." (PMID 26156017, 2015). "Despite these advances, little is known about the role of FLI1 in metastasis, particularly in breast cancer." (PMID 26156017, 2015). "The role of FLI1 in breast cancer metastasis was evaluated by cell migration, invasion, and adhesion assays." (PMID 26156017, 2015). "Congruently, immunohistochemical staining of clinical samples revealed that FLI1 was overexpressed in breast cancers as compared with the adjacent tissues." (PMID 26156017, 2015). "To determine the clinical significance of FLI1, we examined its expression pattern in tumor samples collected from breast cancer patients." (PMID 26156017, 2015). "In this communication, we examined the oncogenic activation of FLI1 and its correlation with clinicopathological features in patients with breast cancer." (PMID 26156017, 2015). "For comparison, we calculated the expression score for FLI1 and compared FLI1 score between breast cancer and adjacent tissues." (PMID 26156017, 2015). "We then used Western blot to compare the expression of FLI1 in five breast cancer cell lines that show varied metastatic abilities." (PMID 26156017, 2015). "This study thus identifies FLI1 as an attractive target for therapeutic intervention in breast cancer." (PMID 26156017, 2015). "Correspondingly, we found a dose-dependent inhibition of cell proliferation with FLI1 knockdown in these two breast cancer cells." (PMID 26156017, 2015). "To determine the role of FLI1 in cell migration, we knocked down FLI1 with siRNAs in two highly metastatic human breast cancer cell lines (MDA-MB231 and MDA-MB453)." (PMID 26156017, 2015). "Knockdown of FLI1 with small interfering RNAs significantly attenuated the potential of migration and invasion in highly metastatic human breast cancer cells." (PMID 26156017, 2015). "In this FLI1/Rho/AKT pathway, overexpression of FLI1 in breast cancer activates the Rho GTPase family genes, either directly or by modulating the RhoGDI inhibitor." (PMID 26156017, 2015). "Friend Leukemia Virus Integration 1 (FLI-1), belonging to the E26 transformation-specific (Ets) transcription factor family, has gained recognition as an oncogene implicated in several malignancies, including breast cancer." (PMID 38473804, 2024). "MECOM and FLI1 activities were decreased, while breast cancer promoted FOSB and RFX2 activities." (PMID 37153595, 2023).
breast carcinoma (continued). "For example, a study has reported that FLI1 exonic circular RNA utilizes a positive feedback mechanism to activate the transcription of FLI1 by inducing DNA hypomethylation in CpG islands of the promoter, which drive the metastasis of breast cancer." (PMID 35965538, 2022). "For example, FECR1, a circRNA derived from exons 2, 3, and 4 of the FLI1 gene, could bind to the promoter of FLI1 and then activate FLI1 by inducing DNA hypomethylation in CpG islands of the promoter, thus promoting the metastasis of breast cancer." (PMID 35281849, 2022). "Another such example is FECR1, a circRNA consisting of FLI1 4-2-3 exons, which is able to recruit TET1 DNA demethylase on the FLI1 promoter inducing DNA demethylation, thus promoting greater expression of FLI1 gene and consequently favoring the invasion of breast cancer cells." (PMID 34202482, 2021). "However, recent studies have reported that Fli-1 is also abnormally expressed in various malignant tumor tissues, such as breast cancer, small-cell lung cancer, and bladder cancer cells." (PMID 32210104, 2020). "Our findings may provide useful help for recognizing the relationship between tumour immune microenvironment and FLI1, and may unravel clinical outcomes and immunotherapy utility for FLI1 in breast cancer." (PMID 32249526, 2020). "The study of Fli-1 in epithelial-derived adenocarcinoma was limited to breast cancer." (PMID 32210104, 2020). "However, the role of Fli-1 in breast cancer remains controversial to date, as several studies have also shown that Fli-1 can inhibit cell apoptosis or promote tumor progression." (PMID 32210104, 2020). "Fli-1 expression has been was observed in various breast cancer cell lines, such as MDA, MB231, MB436, BT-549, and HCC1395; further, 31% of patients with mammary medullary carcinoma express Fli-1, suggesting that it is associated with the occurrence of malignant breast tumors." (PMID 32210104, 2020). "In a murine breast cancer model, Fli1 was shown to act as a tumor suppressor, but studies examining human breast cancer showed that FLI1 enhances tumor properties and that its expression correlates with poor prognostic factors such as lymph node metastasis and poor differentiation." (PMID 31231464, 2019). "Currently, to the best of our knowledge, no study has elucidated the association between FLI‐1 and the prognosis of breast cancer." (PMID 29869379, 2018). "Moreover, the expression of FLI‐1 was lower during the early stage and higher during the advanced stage of breast cancer (P = .007)." (PMID 29869379, 2018). "We hypothesized that these components might actively participate in the control of FLI1 in the development of breast cancers." (PMID 30537986, 2018). "Through the correlation analysis between FLI‐1 and the clinicopathological features of breast cancer, we found that the expression of FLI‐1 was higher in patients with breast cancer with lymph node metastasis compared with that in patients without metastasis (P = .02)." (PMID 29869379, 2018). "Targeting FLI‐1 might eliminate the mesenchymal and stem cell traits and would be a novel approach to improve the prognosis of breast cancer." (PMID 29869379, 2018). "Therefore, the expression of FLI‐1 will be a novel independent and an extremely useful factor indicating poor prognosis in patients with breast cancer." (PMID 29869379, 2018). "Future studies are needed to address whether the FLI1 gene may undergo subtle genetic alterations in solid tumors, including breast cancer." (PMID 30537986, 2018). "Our data thus suggest that FLI1 may regulate the Rho GTPase pathway in breast cancer, at least partially by controlling the activity of the RhoGDIs." (PMID 26156017, 2015). "To test whether FLI1 is functionally important in breast cancer, we used two small interference RNAs (siFLI1 1# and siFLI1 2#) to knockdown FLI1 in MDA-MB231 and MDA-MB453 cells." (PMID 26156017, 2015).
breast carcinoma (continued). "Cell apoptosis was also analyzed after the knockdown of FLI1 in these two breast cancer cells." (PMID 26156017, 2015). "Consequently, knockdown of FLI1 attenuates the metastatic potential in highly aggressive breast cancer cell lines." (PMID 26156017, 2015). "Thus, the oncogenic role of FLI1 in breast cancer metastasis, as observed in the present study, must be mediated through a distinct mechanism." (PMID 26156017, 2015). "However, little is known about the role of FLI1 in other solid tumors, particularly in breast cancer." (PMID 26156017, 2015). "Similarly, Fli-1 has been shown to contribute to the high malignancy of the breast cancer cell line MDA-MB231 whereas another study independently showed the inhibition of Hbp1 by miR-17 in the same cells." (PMID 23056458, 2012). "CircRNAs from exons of FLI1 could function as novel oncogenic drivers in lung and breast cancers." (PMID 35647294, 2022). "Immunotherapy for breast cancer is an active field of investigation, and the higher immunogenicity exhibited by the high expression FLI1 subtype compared to the low expression FLI1 subtype indicated that immunotherapy could be a viable option for the patients with the high FLI1 expression level." (PMID 32249526, 2020). "Furthermore, FLI‐1 can be an independent prognostic factor for breast cancer." (PMID 29869379, 2018). "Furthermore, it had relevance with molecular subtypes, indicating that FLI‐1 might be related to poor outcomes in patients with breast cancer." (PMID 29869379, 2018). "Thus, FECR1 specifically interacted with the FLI1 promoter in breast cancer cells." (PMID 30537986, 2018). "The dysregulation of Fli1, observed in aggressive TNBC cell lines suggests its potential role in driving breast cancer progression." (PMID 40694594, 2025). "In several breast cancer cell lines (MDA-MB231, MDA-MB436, BT-549 and HCC1395) and T- or B-lymphoblastic lymphomas, FLI-1 is highly expressed." (PMID 39107790, 2024). "miR-200 was found to inhibit CAF activation and ECM remodeling by targeting FLI1 and TCF12, thereby interfering with the invasion and metastasis of breast cancer cells." (PMID 38766528, 2024). "Immunotherapy is a practical therapeutic approach in breast cancer (BRCA), and the role of FLI1 in immune regulation has gradually been unveiled." (PMID 38448802, 2024). "In breast cancer, transcriptional upregulation of CDHI and VIM by FLI1 contributes to invasion and migration, and upregulation of BCL2 inhibits apoptosis." (PMID 36814284, 2023). "The circRNA FECR1, which is generated from the Friend leukemia virus integration 1 (FLI-1) oncogene, recruits TET1 to the promoter of FLI-1 and promotes breast cancer metastasis." (PMID 36861443, 2023). "For instance, the positioning patterns of HES5 and FLI1 are highly indicative of cancer, with both HES5 and FLI1 repositioned in 100% of breast cancers and FLI1 repositioned in 92.9% of prostate cancers, compared to benign tissue controls." (PMID 31681438, 2019). "Using a CRISPR Cas9-guided immunoprecipitation assay, we identify a circular RNA in the FLI1 promoter chromatin complex, consisting of FLI1 exons 4-2-3, referred to as FECR1.Overexpression of FECR1 enhances invasiveness of MDA-MB231 breast cancer cells." (PMID 30537986, 2018). "We constructed a lentiviral vector containing the catalytically inactive CRISPR Cas9 (dCas9) and two FLI1 promoter gRNAs and transfected it into MDA-MB231 breast cancer cells." (PMID 30537986, 2018). "From the results of immunohistochemistry, we found that FLI‐1 was overexpressed in the HER2 positive and TNBC subtypes when compared to that in the luminal subtypes of breast cancer." (PMID 29869379, 2018). "To explore the molecular components that activate FLI1 in breast cancer, we utilized a CasIP assay to identify a FECR1 circular RNA that interacts with the FLI1 promoter." (PMID 30537986, 2018).
breast carcinoma (continued). "Knockdown of FLI1 using shRNAs dramatically downregulated RhoGDIs, in parallel with the reduced migration and invasion of MDA-MB-231 breast cancer cells." (PMID 26156017, 2015). "Moreover, FECR1 [a circular RNA of Friend leukemia virus integration 1 (FLI1)], was shown to recruit TET1 to the promoter of FLI1 oncogene, which leads to promoter hypomethylation and FLI1 oncogene overexpression in breast cancer cells." (PMID 35646706, 2022). "FECR1 was a novel circRNA consisting of FLI1 exons 4-2-3, bound to the promoter of FLI1 and recruited DNA demethylase TET1 to induce DNA demethylation, increasing FLI1 expression and promoting invasion of breast cancer cells." (PMID 33643900, 2020). "The present study demonstrates a non-canonical function for the FLI1 in the development of breast cancer." (PMID 30537986, 2018). "Therefore, we further investigated the correlation between FLI‐1 and the CSC phenotype of breast cancer cells." (PMID 29869379, 2018). "p-AKT was significantly inhibited when FLI1 was interfered, thus supporting the concept that FLI1 may activate the AKT pathway in breast cancer cells." (PMID 26156017, 2015). "They found circFECR1 in the FLI1 promoter chromatin complex, and this circular RNA could enhance metastasis in breast cancer by epigenetic mechanisms rather than canonical oncoprotein pathway." (PMID 33277969, 2022). "For example, TGF-β secreted by breast cancer cells has been reported to induce a CAF phenotype in normal fibroblasts by down-regulating miR-200 and up-regulating transcription factor 12 (TCF12) and friend leukemia virus integration 1 (Fli-1) expression, thereby contributing to ECM remodeling." (PMID 32957712, 2020). "The molecular constituents of FECR1/FLI1/TET1 employ a feedback loop to stimulate this through promoting DNA hypomethylation in the CpG islands of the promoter, ultimately controlling the metastasis of breast cancer (BC) cells." (PMID 39452835, 2024). "Three breast cancer cell lines (MDA-MB468, MDA-MB453, and ZR75-1) exhibited weak expression of FLI1, while the non-aggressive MCF-7 was almost negative for FLI1." (PMID 26156017, 2015). "In this report, we found that Friend leukemia virus integration 1 (FLI1) proto-oncogene was differentially expressed between the aggressive MDA-MB231 and the non-aggressive MCF-7 breast cancer cells." (PMID 26156017, 2015). "FLI1 was a specific target in the erythroleukemia HEL cells, and FLI1 inhibitors were developed to treat erythroleukemia in our previous study Herein, we showed that L1 selectivity and specificity inhibited the erythroleukemia HEL cell line rather than in breast cancer cell lines." (PMID 40822462, 2025).
leukemia (43 papers, 2011 to 2025). A malignant (clonal) hematologic disorder, involving hematopoietic stem cells and characterized by the presence of primitive or atypical myeloid or lymphoid cells in the bone marrow and the blood. "Our analysis of AM chemical composition described herein identified four compounds (Ba, Ka, He, and Fn) exhibiting strong anti-FLI1 activity, associated with the induction of differentiation, apoptosis, and inhibition of leukemia proliferation." (PMID 39769192, 2024). "Although most common in EWS, EWSR1::FLI1 fusions have rarely been described in hematopoietic malignancies including acute leukemias, myeloid sarcoma, and in secondary leukemia after a diagnosis of EWS." (PMID 40630716, 2025). "As FLI1 knockdown blocks leukemia cell proliferation, we next examined impact of UBASH3A and UBASH3B on cell growth." (PMID 38461240, 2024). "Another study published contradictory results, demonstrating significantly high FLI-1 positivity in several T-cell lymphomas, including precursor lymphoblastic lymphoma/leukemia and other mature T-cell lymphomas." (PMID 38280044, 2024). "In this study, we show that leukemias expressing high FLI1 produce either higher UBASH3B or lower UBASH3A." (PMID 38461240, 2024). "We identified at least four compounds within AM/Ai with anti-FLI1 activity, resulting in suppression of leukemia." (PMID 39769192, 2024). "Herein, we showed that loss of FLI1 and consequently its downstream target UBASH3B in leukemia cells increased AP1 expression, leading to proliferation suppression and increased apoptosis." (PMID 38461240, 2024). "Consistent with the critical role of Fli-1 activation in leukemia and in this animal model, we found that AM/Ai strongly inhibits this ETS member in the culture of various leukemic cells leading to cell cycle arrest and apoptosis." (PMID 39769192, 2024). "Ba-induced Kyn metabolic activity slightly increased in Ba + IFN-γ treated cells, indicating a marginal role for FLI1 in this enzymatic process in leukemia." (PMID 39769192, 2024). "Overall, this study demonstrates for the first time the important contribution of at least four AM components in blocking FLI1 function, leading to leukemia inhibition." (PMID 39769192, 2024). "The balance between oncogenic and tumor suppressor activity of UBASH3B and UBASH3A, respectively, likely contributes to FLI1-induced leukemia cell proliferation." (PMID 38461240, 2024). "Being initially described as a factor of virally-induced leukemias, Fli1 (Friend leukemia integration 1) has attracted considerable interest lately due to its role in both healthy physiology and a variety of pathological conditions." (PMID 36768203, 2023). "FLI1 is a transcription factor exhibiting high expression in leukemias, while its knockdown was shown to significantly hinder cell proliferation of leukemic cell lines." (PMID 37424436, 2023). "As Fli-1 activation is critical for murine leukemia induction by F-MuLV, we tested for Fli-1 levels." (PMID 37016335, 2023). "It was worth mentioning that two compounds (14 and 24) were firstly found as the potential lead compounds with a good effect on the Fli-1 gene in leukaemia." (PMID 34301301, 2021). "As the Fli-1 gene is a new target for drug screening, we sought to investigate the involvement of inhibitory effects on Fli-1 against leukaemia by active compounds of Z. nitidium." (PMID 34301301, 2021). "Our study demonstrates that Fli-1 inhibition by the diterpenoid compounds upregulates miR-145 expression, leading to downregulation of Fli-1 and consequently to inhibition of leukemia." (PMID 30741932, 2019). "ShRNA-mediated knockdown of miR-145 in drug-treated leukemias only partially rescued survival, indicating the importance of other Fli-1 targets during leukemogenesis." (PMID 30741932, 2019). "Overall, our results demonstrate that some of our PKCAs, such as A75, can be utilized for the treatment of leukemia carrying an activated Fli-1." (PMID 28052010, 2017).